CXCR4 (C-X-C motif chemokine receptor 4)
Diseases named in the same sentence as CXCR4 in open-access papers (continued):
Sharing a sentence is not in itself a finding about the gene and the disease.
tumor (continued). "These interactions represent an indirect mechanism mediating CXCL12/CXCR4-dependent promotion of survival, proliferation and migration of tumor cells." (PMID 24904289, 2014). "CAFs also cooperate with tumor cells to promote angiogenesis through CXCR4 expressed by both cell types." (PMID 25110692, 2014). "We found that expression of BCL6 increased tumor cell viability, migration, invasion, and survival as well as expression of cyclinD1, and CXCR4 in vitro." (PMID 24917186, 2014). "Tumor cells cultured in hypoxic conditions, for example, showed significant overexpression of CXCR4." (PMID 24591761, 2014). "Dysregulation of HIF and/or cytokines, such as the CXCR4/CXCR7/CXCL12 axis, is one probable cause of increased angiogenesis via the overexpression of tumor VEGF." (PMID 24629239, 2014). "CXCR4 seems to be a relevant target, as CXCR4 remains continuously expressed when tumor cells switch from a hypoxic to a normoxic environment." (PMID 24629239, 2014). "This notion is supported by the evidence that the activation of CXCR4 leads to lung cancer cell migration and adhesion to stromal cells, which in turn provides growth- and drug-resistance signals to the tumor cells." (PMID 24971349, 2014). "Little is known about the transcriptional regulation of CXCR4 and its importance in tumor microenvironment." (PMID 25114911, 2014). "The chemokine CXCL12 has been recognized as an important chemoattractant of CXCR4 expressing metastasizing cells of numerous tumor types." (PMID 24390633, 2014). "To determine the effect of CXCR4 inhibition on tumor angiogenesis we measured hotspots of angiogenesis in primary and lymph node metastatic tumor tissues for CD34 positive blood vessels." (PMID 24472670, 2014). "CXCR4 expression was found to be significantly increased in the tumors and correlated with the tumor grade, whereas the expression of CXCL12 was significantly decreased in the tumors compared with the healthy samples." (PMID 24906407, 2014). "Recently, it was proposed that inhibition of CXCR7 on endothelial cells coupled with inhibition of CXCR4 on CD11b+ monocytes can inhibit the post-irradiation recovery of the vasculature and delay local tumor recurrence." (PMID 25084358, 2014). "The prominent role of this axis in tumor growth and cancer stem-like cells' interaction with their microenvironment and the perivascular space, designed CXCR4 as a potential target for adjuvant chemotherapies." (PMID 24662753, 2014). "CXCR4 is expressed in various tumor cells, and the CXCR4/SDF-1 axis has a significant role in malignant tumor genesis, adhesion, infiltration and metastasis." (PMID 25202367, 2014). "Within the chemokines in cancer, the CXCR4/CXCL12 axis is currently best characterized and CXCR4 is a ubiquitously expressed receptor on tumor cells." (PMID 25254213, 2014). "Another physical and chemical factor, radiation, exerts a similar effect through CXCR4/CXCL12 interaction on tumor angiogenesis." (PMID 25110692, 2014). "NSCLC tumors and cell lines express CXCR4, and, in mouse models, anti-CXCR4 antibody reduces tumor metastases." (PMID 25271023, 2014). "Although the migration inhibition is only partial (40%), the fact that a higher chalcone concentration (10 μM) inhibits migration by 80%, is clearly in favor of the involvement of CXCL12 via CXCR4 in the tumor cell migration process." (PMID 24629239, 2014). "CXCR4 is considered to be the major chemokine receptor expressed on cancer cells and its expression is required for tumor metastasis to other organs; CXCR4 activation by CXCL12 induces the migration of neoplastic cells." (PMID 24348776, 2014). "High CXCL12 levels in the tumor attract CXCR4-positive inflammatory, vascular and stromal cells into the tumor mass, where they will eventually support the tumor growth by secreting growth factors, cytokines, chemokines, and pro-angiogenic factors." (PMID 25471741, 2014).
tumor (continued). "These authors analyzed the relationship between SDF-1 and CXCR4 expression and the tumor's potential for myometrial invasion." (PMID 24416254, 2014). "CXCR4 antibody treatment inhibited 143B-lacZ cell homing to the lung and had a mild inhibitory effect on primary tumor osteolysis and growth." (PMID 24390633, 2014). "The higher expression of CXCR4 in tumor tissue correlates with poor prognosis in colorectal cancer patients." (PMID 24971349, 2014). "To show the expression of CXCR4 in squamous epithelial cell of normal cervical tissue, we did the immunohistochemistry in five normal and eight tumor biopsy samples." (PMID 25114911, 2014). "CXCR4 has been known to be overexpressed in more than 20 human tumor types, and CXCR4 antagonists inhibit tumor growth in multiple experimental orthotopic, subcutaneous human xenografts, and transgenic mouse models." (PMID 25471741, 2014). "Immunohistochemical staining was performed in order to detect the expression of CXCR4 in tumor HCC tissues and of SDF-1α in the tissues adjacent to the HCC ones." (PMID 24912495, 2014). "Activation of the immune pathway is important for tumor shrinkage; SDF1α and its receptor CXCR4 play important roles in immune function and have the potential to enhance anticancer immunity." (PMID 25047123, 2014). "Pharmacological inhibition of HIF1α or the CXCL12/CXCR4 axis reduced BM-derived cell recruitment and prevented tumor recurrence." (PMID 25526031, 2014). "The CXCL12/CXCR4 pathway plays a pivotal role in several aspects of tumor progression including vascularization, metastasis and survival." (PMID 24647809, 2014). "A growing body of evidence has demonstrated that the CXCL12/CXCR4 axis and Rho signaling pathway play critical roles in cell migration, chemotaxis, tumor metastasis, and actin stress fiber formation." (PMID 25121739, 2014). "Further corroboration of these findings came from studies showing higher CXCR4 expression in GBM CSC cultures than in the differentiated tumor cells obtained from the same culture." (PMID 24904289, 2014). "As described in previous studies, the SDF-1/CXCR4 axis significantly promotes cell migration, enhances microvascular endothelial cell tube formation and tumor metastasis." (PMID 24505417, 2014). "SDF-1 -CXCR4 axis has been shown to direct tumor cells to organs that highly express SDF-1 e.g., lymph nodes, lungs, liver or bones." (PMID 24728301, 2014). "The results revealed that miR-126 function as a tumor suppressor in CRC cells by regulating CXCR4 expression via the AKT and ERK1/2 signaling pathways." (PMID 25255814, 2014). "Inhibition of CXCR4 by peptide antagonist CTCE-9908 resulted in a 45% inhibition of primary tumor growth and a 42% reduction of VEGF expression levels." (PMID 24971349, 2014). "The preliminary results demonstrated that CXCR4 expression levels in the tumor tissue of NSCLC patients with brain-specific metastasis is higher compared with NSCLC patients without distant metastases." (PMID 24932250, 2014). "Nevertheless, in our in vivo experiments, the expression of CXCR4 in tumor tissues, as well as the expression of SDF-1α in the tissues adjacent to the HCC ones, was increased following FK506 treatment." (PMID 24912495, 2014). "Previous studies have indicated that CXCR4 is expressed in a number of tumor cells, and its specific binding with SDF-1 in certain tissues is key for tumor genesis, progression and metastasis." (PMID 25202367, 2014). "When injected into mice, CXCR4 knock-down cells produced a decrease in tumor growth and an increase in survival." (PMID 24936477, 2014). "Higher expressions of CXCR1, CXCR2, and CXCR4 with their ligands CXCL5, CXCL8, and CXCL12 appear to be associated with tumor angiogenesis, metastasis, and poor survival in NSCLCs." (PMID 25271023, 2014).
tumor (continued). "The stroma-secreted chemokine, stroma derived factor 1α (SDF-1α, or termed as CXCL12), and its cognate receptor, the chemokine receptor 4 (CXCR4) are two very key mediators in the cross-talking between tumor cells and their microenvironment." (PMID 25312253, 2014). "Recent studies have reported on the overexpression of the chemokine receptors CXCR4 and CXCR7 by several tumor entities and have shown that CXCR4 plays a crucial role in organ-specific metastasis formation." (PMID 24629239, 2014). "Stromal fibroblasts support the growth of neoplastic cells through elevated secretion of CXCL12, and integrins induce expression of CXCR4 and growth-factor receptors sustaining a pro-survival loop for tumor cells." (PMID 24904289, 2014). "CXCL12 expression in tumor endothelial cells and CXCR4 expression on metastatic tumors were found to correlate with shorter patient survival, indicative of a more aggressive tumor group." (PMID 24857921, 2014). "In the survival analysis, patients with strong expression of CXCR4 on their tumour tissues profited more in terms of overall survival under the treatment of FLP." (PMID 24981311, 2014). "A previous study showed that CXCL12/CXCR4 axis signaling induces actin stress fiber formation, and regulates tumor spread and metastasis." (PMID 25121739, 2014). "We first demonstrated that intravenous injected 111In-oxine labelled ECFCs are able to home into tumor mass by exploiting the CXCR4/SDF1 axis." (PMID 25003596, 2014). "CXCR4 seems to be a relevant target because it is continuously expressed and functional both in normoxic and hypoxic conditions in tumor cells." (PMID 24629239, 2014). "In relation to the tumor microenvironment, pathological involvement of the chemokine (C-X-C motif) ligand 12/chemokine (C-X-C motif) receptor 4 (CXCL12/CXCR4) signaling axis has been very well documented in several malignancies, including PCa." (PMID 25359780, 2014). "The significance of the CXCL12/CXCR4 signaling axis in breast and other tumor progression and invasiveness has been reported by many investigations (6, 16, 17 and 18)." (PMID 25237365, 2014). "They observed that the tumor level of CXCR4 mRNA was higher and the level of SDF-1 expression lower than in normal tissue." (PMID 24416254, 2014). "Our work suggests that SDF-1/CXCR4 autocrine signalling can play an important role in regulating tumour survival and is consistent with the observation that activation of this pathway reduces apoptosis in serum-starved murine embryonic stem cells." (PMID 25162584, 2014). "CXCL12 (previously known as stromal cell-derived factor-1, SDF-1) is an exception to this characterization, since it is ELR− but mediates tumor-promoting angiogenesis via its receptor CXCR4." (PMID 25484899, 2014). "A high expression of CXCR4 in the primary CRC tumor is considered an independent prognostic factor for poor disease-free survival, and nuclear distribution of CXCR4 is reported to have an inverse relationship with disease-free and overall survival." (PMID 24647809, 2014). "Patients with strong expression of CXCR4 on their tumour tissues profited more in terms of OS under the treatment of FLP (mOS: 28 vs 15 months, p = 0.05 respectively)." (PMID 24981311, 2014). "The previous views also suggested that tumor cells express high CXCR4, and the metastasis-targeted organs express high CXCL12, so the tumor cells were attracted to the ligand in these organs." (PMID 24810923, 2014). "U87 xenografts are highly angiogenic and prior studies using them have identified tumor cell and microvascular targets for CXCR4 antagonism." (PMID 25238146, 2014). "Ligand-induced endocytosis of CXCR4 and its internal sequestration has been extensively studied in leukocytes and to a lesser degree in hematopoietic stem cells and tumour cells." (PMID 24885150, 2014).
tumor (continued). "The results of previous studies using various cancer cell lines have shown that inhibition of CXCR4 reduces the frequency of metastasis, indicating that the receptor is essential for tumor cell dissemination and invasion of tissues." (PMID 24944647, 2014). "Of interest, we identified an enrichment of genes involved in the CXCR4 signaling pathway or in the interactions between the CLL tumor cells and their microenvironment (CCL3, CCL4, and CD49d)." (PMID 24883311, 2014). "Immunohistochemical analyses have shown that CXCL12 is highly expressed in hepatic sinusoids including endothelial and Kupffer cells and that disseminating tumor cells express CXCR4." (PMID 24629239, 2014). "The CXCR4 expression in tumour tissues showed a strong impact on survival in both treatment groups FLO and FLP." (PMID 24981311, 2014). "Among the family of chemokine and chemokine receptors mediating tumor cell invasion and metastasis, CXCL12/CXCR4 has gained a central role in different types of tumors in mediating tumor growth, angiogenesis and metastasis." (PMID 24472670, 2014). "CXCR4 is the most common chemokine receptor expressed on tumour cells and has been detected in 23 different types of cancer." (PMID 24583601, 2014). "Nevertheless, when combining inhibition of SDF-1/CXCR-4 interactions with radiation, a fractionated low-dose regimen (2 Gy × 5) and a single high-dose (15 Gy) both resulted in complete anti-tumor responses." (PMID 24478982, 2014). "In vitro assays, including CCK-8 assay, flow cytometry, and colony formation assay, and in vivo tumor formation assay were utilized to detect the cell phenotype of CXCR4 knockdown cells." (PMID 25471741, 2014). "Among all chemokine receptors known to be involved in the progression of different cancers including LuCa, CXCR4 is expressed in majority of cancers and plays an important role in dissemination and homing of primary tumor at distant sites." (PMID 25296976, 2014). "AMD3100 is a bicyclam CXCR4 inhibitor that has been shown to be effective in reducing tumor growth in glioblastoma and peritoneal metastasis in ovarian carcinoma." (PMID 24472670, 2014). "SDF-1 also promotes tumor development by stimulating angiogenesis and by processing the metastasis of CXCR4-positive tumor cells to distant organs producing SDF-1." (PMID 24929539, 2014). "A CXCR4 antagonist, d-Arg3FC131, was shown to induce apoptosis and suppress the proliferation of somatotrope tumor cells." (PMID 24647809, 2014). "Differential downregulation of CXCR4 in tumor biopsy samples indicates antitumor activity of SDF-1α/CXCR4 signaling." (PMID 25114911, 2014). "Our previous preliminary study demonstrated that CXCR4 overexpression in tumor tissue is correlated with NSCLC at the homeochronous and heterochronic phases of solitary brain metastasis." (PMID 24932250, 2014). "The CXCL12/CXCR4 axis is known to be involved in several aspects of tumor progression including angiogenesis, metastasis, and survival." (PMID 24674692, 2014). "Targeting CXCR4 can have dual effects on inhibiting primary tumor growth and metastasis or mono effect on inhibiting either tumor growth or metastasis." (PMID 24472670, 2014). "Natural ligands and TZDs have reduced CXCR4 expression in tumor cells in a model of metastasizing cancer." (PMID 25191225, 2014). "Concordant with RT PCT and immunoblotting, CXCR4 was expressed in normal cervical squamous epithelial cell which was differentially downregulated in tumor tissue." (PMID 25114911, 2014). "Since it is reported that the tumor tropism of NSCs is regulated by hypoxia-related signaling pathways, the mRNA expression alternation of hypoxia-related signal receptors, c-Met, CXCR4, c-Kit, and VEGFR2, in NSCs upon hypoxia treatment was measured by qPCR." (PMID 24864258, 2014). "This study demonstrates epigenetic silencing of CXCR4 in CC cell lines and tumor biopsy samples by promoter hypermethylation and histone deacetylation." (PMID 25114911, 2014).
tumor (continued). "Previous studies have demonstrated that CXCR4 is the most common chemokine receptor expressed in tumor cells, and that it plays a predominant role in the migration and invasion of tumors." (PMID 24959222, 2014). "Several novel CXCR4 antagonists have shown promising in vitro anti-cancer activity in several tumor cell types, including those derived from breast." (PMID 23484027, 2013). "CXCL12 is also constitutively expressed in tissues such as liver, lung, lymph nodes, adrenal glands and bone marrow, which indicates the important role of CXCL12/CXCR4 in tumor metastasis toward distant locations." (PMID 23555768, 2013). "In the current study, Pearson’s correlation coefficient and a linear regression analysis were applied to evaluate the correlations between the expression levels of MIF and CXCR4 in tumor cells and TILs." (PMID 23497377, 2013). "Using a human tumor metastasis PCR array, it was observed that numerous tumor-associated genes were upregulated in the CD24+ cells, including CXC chemokine receptor type 4 (CXCR4)." (PMID 24179538, 2013). "Based on recently published findings of Zabel and co-workers, who demonstrated that CXCR4/CXCR7 co-expressing lymphoblastic tumor cells exhibited significantly enhanced trans-endothelial migration compared to cells expressing CXCR4 alone." (PMID 24040160, 2013). "HIF-2α promotes metastasis through regulation of critical factors controlling tumor cell metastatic potential, such as CXCR4 and TWIST." (PMID 24288553, 2013). "In tumors, SDF-1/CXCR4 signaling has been shown to regulate vascularization of tumors, to foster tumor growth, and to mediate homing of tumor cells to metastatic sites." (PMID 23593347, 2013). "CXCR4 is not only expressed by tumor cells, but can also be expressed by native immune cells such as lymphocytes." (PMID 23326303, 2013). "Targeting of CXCR7 also inhibits SDF-1α/CXCR4-mediated transendothelial migration of human tumor cells." (PMID 23865743, 2013). "Recent studies have shown that TWIST and CXCR4 are two direct target genes of HIF-2α, HIF-2α can activate the expression of TWIST and CXCR4, which subsequently promote invasion and metastasis of tumor cells." (PMID 24288553, 2013). "It was previously reported that the CXCL12 / CXCR4 axis was essential for metastatic cancer cells to disperse to organs and thereby allow tumor cells to access cellular niches that favor tumor-cell survival and growth." (PMID 24312338, 2013). "Conversely, the levels of CXCR4 protein were elevated in 52.63% (10/19) of the tumors when compared to their corresponding non-tumor tissues." (PMID 24330809, 2013). "The CXCR4/CXCL12 chemotactic gradient has been proposed as a mechanism for tumor cell homing to distant metastatic sites." (PMID 24278179, 2013). "Taken together, these studies demonstrate that CXCL12/CXCR4 signaling is a critical event mediating homing of tumor cells and subsequent expansion of metastases." (PMID 23902739, 2013). "We have previously shown that, similar to tumour-associated TEMs, Phd2+/− macrophages do not upregulate either Vegf or inflammatory genes, but instead express increased levels of Tie2, Nrp1, Cxcr4, Pdgfb and Sdf1, which together may enhance their proarteriogenic capacity." (PMID 23616286, 2013). "The expressions of MIF and CXCR4 proteins in tumor cells and TILs have different clinically predictive values in ESCC." (PMID 23497377, 2013). "Previous studies have investigated the effects of CXCR4 antagonism on tumor growth and metastasis in other xenograft models." (PMID 24137439, 2013). "By combining click beetle bioluminescence with whole animal fluorescence imaging, we were able to analyze changes in CXCR4 signaling relative to total tumor burden over extended periods of time in the same cohort of mice." (PMID 23372646, 2013).